KCNJ8 (potassium inwardly rectifying channel subfamily J member 8)
Description:
Inward rectifier potassium channels are characterized by a greater tendency to allow potassium to flow into the cell rather than out of it. Their voltage dependence is regulated by the concentration of extracellular potassium; as external potassium is raised, the voltage range of the channel opening shifts to more positive voltages. The inward rectification is mainly due to the blockage of outward current by internal magnesium. This channel is activated by internal ATP and can be blocked by external barium. Can form a sulfonylurea-sensitive but ATP-insensitive potassium channel with ABCC9 (By similarity).
Synonyms: Kir6.1; uKATP-1
Tractability: Small molecule: an approved drug acts on it; it belongs to a druggable protein family. Antibody: its Gene Ontology location is reachable by antibodies, with high confidence; UniProt predicts a signal peptide or a membrane-spanning region. PROTAC: a small molecule that binds it is known.
Target class: Inwardly rectifying potassium channel; Potassium channels; Voltage-gated ion channel; Ion channel
Safety:
Unwanted effects reported when the protein is acted on. In parentheses: how it was acted on, where the effect was seen, and who reports it.
abnormal pulse (activation, acute dosing; pancreas, renal, cardiovascular; source: Lynch et al. (2017))
atrioventricular block (inhibition, acute dosing; pancreas, renal, cardiovascular; source: Lynch et al. (2017))
cardiac arrhythmia (activation, acute dosing; pancreas, renal, cardiovascular; source: Lynch et al. (2017))
cardiac lesions (activation, acute dosing; pancreas, renal, cardiovascular; source: Lynch et al. (2017))
decreased blood glucose (inhibition, acute dosing; pancreas, renal, cardiovascular; source: Lynch et al. (2017))
decreased blood insulin (activation, acute dosing; pancreas, renal, cardiovascular; source: Lynch et al. (2017))
decreased blood pressure (activation, acute dosing; pancreas, renal, cardiovascular; source: Lynch et al. (2017))
decreased convulsions (activation, acute dosing; pancreas, renal, cardiovascular; source: Lynch et al. (2017))
decreased heart rate (inhibition, acute dosing; pancreas, renal, cardiovascular; source: Lynch et al. (2017))
increased blood insulin (inhibition, acute dosing; pancreas, renal, cardiovascular; source: Lynch et al. (2017))
increased heart rate (activation, acute dosing; pancreas, renal, cardiovascular; source: Lynch et al. (2017))
increased urinary sodium excretion (inhibition, acute dosing; pancreas, renal, cardiovascular; source: Lynch et al. (2017))
increased urine excretion (inhibition, acute dosing; pancreas, renal, cardiovascular; source: Lynch et al. (2017))
increased/decreased blood glucose (activation, acute dosing; pancreas, renal, cardiovascular; source: Lynch et al. (2017))
Gene: Protein-coding gene on chromosome 12 (21,764,950 to 21,775,615, reverse strand). Ensembl gene ENSG00000121361.
Subcellular location: Membrane
Pathways (Reactome):
Neuronal System: ATP sensitive Potassium channels
Gene Ontology:
Molecular function: ATP-activated inward rectifier potassium channel activity; protein binding; voltage-gated monoatomic ion channel activity involved in regulation of presynaptic membrane potential; voltage-gated potassium channel activity involved in ventricular cardiac muscle cell action potential repolarization; ATP binding; ATPase-coupled monoatomic cation transmembrane transporter activity; inward rectifier potassium channel activity; sulfonylurea receptor binding; voltage-gated potassium channel activity
Biological process: membrane repolarization during ventricular cardiac muscle cell action potential; potassium ion import across plasma membrane; potassium ion transmembrane transport; potassium ion transport; transmembrane transport; transport across blood-brain barrier; inorganic cation import across plasma membrane; kidney development; regulation of presynaptic membrane potential
Cellular component: plasma membrane; potassium ion-transporting ATPase complex; voltage-gated potassium channel complex; glutamatergic synapse; inward rectifying potassium channel; membrane; myofibril; potassium channel complex; presynapse; presynaptic active zone membrane; sarcolemma
Genetic constraint (gnomAD): Loss-of-function variants: 13 observed, 28.51 expected, observed/expected ratio (o/e) 0.46, 90% interval 0.3 to 0.73. The upper end of that interval is the gene's LOEUF score, 0.73, which puts it in group 2 of 6, group 1 being the genes least tolerant of losing a copy. Missense variants: 284 observed, 571.2 expected, observed/expected ratio (o/e) 0.5, 90% interval 0.45 to 0.55. Synonymous variants: 188 observed, 207.45 expected, observed/expected ratio (o/e) 0.91, 90% interval 0.8 to 1.02.
Gene-disease validity (ClinGen):
ClinGen rates the evidence that KCNJ8 causes each of these diseases.
Brugada syndrome (autosomal dominant): Disputed. A genetically heterogeneous condition characterized by complete or incomplete right bundle branch block accompanied by ST elevation in leads V1-V3.
Homologues: Orthologues: chimpanzee KCNJ8 (100% identical), dog KCNJ8 (99% identical), macaque KCNJ8 (99% identical), pig KCNJ8 (99% identical), rabbit KCNJ8 (99% identical), mouse Kcnj8 (98% identical), guinea pig KCNJ8 (98% identical), rat Kcnj8 (98% identical), tropical clawed frog kcnj8 (85% identical), zebrafish kcnj8 (79% identical), Drosophila melanogaster Irk1 (39% identical), Caenorhabditis elegans irk-2 (37% identical), and 4 more. Paralogues in human: KCNJ11 (64% identical), KCNJ2 (42% identical), KCNJ12 (41% identical), KCNJ18 (41% identical), KCNJ4 (40% identical), KCNJ6 (40% identical), KCNJ5 (39% identical), KCNJ3 (39% identical), KCNJ9 (38% identical), KCNJ14 (36% identical), KCNJ1 (35% identical), KCNJ16 (33% identical), and 3 more.